GGN (gametogenetin)
Description:
May be involved in spermatogenesis.
Synonyms: FLJ35713; MGC33369
Tractability: No criterion of Open Targets' tractability assessment is met for any kind of drug.
Gene: Protein-coding gene on chromosome 19 (38,384,267 to 38,388,274, reverse strand). Ensembl gene ENSG00000179168.
Subcellular location (Human Protein Atlas): Golgi apparatus; Cytosol
Gene Ontology:
Molecular function: protein binding; ubiquitin protein ligase binding; identical protein binding
Biological process: gamete generation; double-strand break repair
Cellular component: perinuclear region of cytoplasm
Genetic constraint (gnomAD): Loss-of-function variants: 25 observed, 29.44 expected, observed/expected ratio (o/e) 0.85, 90% interval 0.62 to 1.19. The upper end of that interval is the gene's LOEUF score, 1.19, which puts it in group 5 of 6, group 1 being the genes least tolerant of losing a copy. Missense variants: 1,005 observed, 888.29 expected, observed/expected ratio (o/e) 1.13, 90% interval 1.07 to 1.19. Synonymous variants: 424 observed, 413.46 expected, observed/expected ratio (o/e) 1.03, 90% interval 0.95 to 1.11.
Homologues: Orthologues: chimpanzee GGN (98% identical), pig GGN (77% identical), mouse Ggn (73% identical), rat Ggn (72% identical), guinea pig GGN (70% identical), dog GGN (60% identical), Caenorhabditis elegans C09F9.2 (25% identical), Drosophila melanogaster nahoda (11% identical), Drosophila melanogaster Vajk3 (6% identical), Drosophila melanogaster Vajk2 (5% identical), Drosophila melanogaster Vajk4 (4% identical). Paralogues in human: ZNF512B (14% identical), ZNF512 (11% identical).
Diseases named in the same sentence as GGN in open-access papers:
GGN is named in the same sentence as 8 diseases in open-access papers, as found by Europe PMC text mining. Sharing a sentence is not in itself a finding about the gene and the disease. The quoted sentences say what the papers report.
Globozoospermia (4 papers, 2020 to 2024). Any structural anomaly of the acrosome resulting in a round sperm head. "The most common abnormality is variation in the DPY19L2 gene, while variations in the SPATA16, PICK1 and GGN have also been investigated as causes of globozoospermia." (PMID 34361119, 2021). "In mice, homozygous knockout of Ggn causes pre-implantation embryonic lethality which precluded the assessment of spermatozoa and as such the role of the identified GGN variants in the etiology of globozoospermia remained unclear." (PMID 33055224, 2020).
amyotrophic lateral sclerosis (1 paper, 2023). Amyotrophic lateral sclerosis (ALS) is a neurodegenerative disease characterized by progressive muscular paralysis reflecting degeneration of motor neurons in the primary motor cortex, corticospinal tracts, brainstem and spinal cord. "The GGNBP2 gene codes for a protein that interacts with gametogenetin during spermatogenesis; the protein is also associated with amyotrophic lateral sclerosis (ALS), ovarian cancer, breast cancer and chromosome 17Q12 deletion syndrome." (PMID 37026480, 2023).
male infertility (1 paper, 2022). The inability of the male to effect fertilization of an ovum after a specified period of unprotected intercourse. "GGN is a testis-enriched gene that has also been implicated to have a role in male infertility too." (PMID 36140773, 2022).
GGN also shares sentences with these, for which no sentence is quoted: breast carcinoma (1 paper); infertile (1); lung carcinoma (1); macrozoospermia (1); ovarian carcinoma (1).